CD101 (CD101 molecule)
Description:
Plays a role as inhibitor of T-cells proliferation induced by CD3. Inhibits expression of IL2RA on activated T-cells and secretion of IL2. Inhibits tyrosine kinases that are required for IL2 production and cellular proliferation. Inhibits phospholipase C-gamma-1/PLCG1 phosphorylation and subsequent CD3-induced changes in intracellular free calcium. Prevents nuclear translocation of nuclear factor of activated T-cell to the nucleus. Plays a role in the inhibition of T-cell proliferation via IL10 secretion by cutaneous dendritic cells. May be a marker of CD4(+) CD56(+) leukemic tumor cells.
Synonyms: IgSF2; EWI-101; V7
Tractability: Antibody: its Gene Ontology location is reachable by antibodies, with high confidence; UniProt predicts a signal peptide or a membrane-spanning region. PROTAC: its protein half-life has been measured.
Gene: Protein-coding gene on chromosome 1 (117,001,721 to 117,036,552, forward strand). Ensembl gene ENSG00000134256.
Subcellular location: Membrane
Subcellular location (Human Protein Atlas): Mitochondria
Pathways (Reactome):
Immune System: Generation of second messenger molecules
Gene Ontology:
Molecular function: hydrolase activity, acting on carbon-nitrogen (but not peptide) bonds, in cyclic amides
Biological process: cell surface receptor signaling pathway
Cellular component: extracellular exosome; membrane; plasma membrane
Genetic constraint (gnomAD): Loss-of-function variants: 76 observed, 103.51 expected, observed/expected ratio (o/e) 0.73, 90% interval 0.61 to 0.89. The upper end of that interval is the gene's LOEUF score, 0.89, which puts it in group 3 of 6, group 1 being the genes least tolerant of losing a copy. Missense variants: 1,145 observed, 1,278.2 expected, observed/expected ratio (o/e) 0.9, 90% interval 0.85 to 0.94. Synonymous variants: 471 observed, 499.55 expected, observed/expected ratio (o/e) 0.94, 90% interval 0.87 to 1.02.
Homologues: Orthologues: chimpanzee CD101 (98% identical), macaque CD101 (95% identical), pig CD101 (76% identical), dog CD101 (76% identical), rabbit CD101 (75% identical), guinea pig CD101 (74% identical), rat Cd101 (71% identical), mouse Cd101 (70% identical). Paralogues in human: IGSF3 (37% identical), PTGFRN (19% identical), IGSF8 (17% identical), VSTM4 (6% identical), VSTM2A (5% identical).
Diseases named in the same sentence as CD101 in open-access papers:
CD101 is named in the same sentence as 58 diseases in open-access papers, as found by Europe PMC text mining. Sharing a sentence is not in itself a finding about the gene and the disease. The quoted sentences say what the papers report.
invasive candidiasis (7 papers, 2016 to 2025). "A phase 2 study is under way, evaluating CD101 as a once-weekly intravenous (i.v.)infusion for the treatment of candidemia and invasive candidiasis." (PMID 29133552, 2018). "CD101 is currently being evaluated as a once-weekly intravenous (i.v.)infusion for the treatment of candidemia and invasive candidiasis." (PMID 29133552, 2018). "With an extended weekly dosing, CD101 showed better prophylactic and treatment efficacies for invasive candidiasis than micafungin." (PMID 29133552, 2018). "CD101 IV, a new echinocandin antifungal drug, is being developed for candidemia and invasive candidiasis." (PMID 27919901, 2017). "CD101 IV is a novel echinocandin with distinctive pharmacokinetic properties that is being developed as a once-weekly treatment for candidemia and invasive candidiasis." (PMID 27919901, 2017). "At this dosing level, CD101 has demonstrated better or at least comparable efficacy in vivo against invasive candidiasis relative to micafungin." (PMID 28739797, 2017). "CD101 is a novel echinocandin with a long half-life undergoing clinical development for treatment of candidemia/invasive candidiasis and vulvovaginal candidiasis." (PMID 27480852, 2016). "CD101 is a novel echinocandin drug being developed to treat severe fungal infections including invasive candidiasis." (PMID 27354115, 2016). "In a murine model of invasive candidiasis, CD101 displayed better or at least comparable efficacy relative to MCF in treating WT or fks mutant Candida albicans." (PMID 27354115, 2016). "Rezafungin (CD101), a next-generation echinocandin, was approved by the FDA in March 2023 and by the EMA in December 2023 for the treatment of invasive candidiasis in adults with limited therapeutic options." (PMID 40863253, 2025).
fungal infections (6 papers, 2016 to 2021). "In 2018, another patent was filed for the use of CD101 alone or in combination with another antifungal drug for the treatment of fungal infections." (PMID 33803604, 2021). "CD101, a novel echinocandin, is in development as an i.v. formulation for the treatment and prevention of serious systemic fungal infections." (PMID 28137817, 2017). "CD101 was as active as the other echinocandins against common fungal organisms recovered from patients with invasive fungal infections." (PMID 28052853, 2017). "Given its low clearance, long half-life, and wide tissue distribution, CD101 once weekly is expected to provide appropriate systemic levels for treatment and prevention of invasive fungal infections." (PMID 28137817, 2017). "In conclusion, the high stability, low clearance, long plasma half-life, and remarkable safety/efficacy profile of CD101 support further development of CD101 as a highly differentiated therapy for the treatment of serious fungal infections." (PMID 27620474, 2016). "In 2017, CD101 (then named rezafungin) was patented for the treatment of fungal infections." (PMID 33803604, 2021). "Our findings support the further development of CD101 as a treatment of invasive fungal infections." (PMID 27620474, 2016). "In studies in beagle dogs, one member of this group, CD101, was distinct from the others in terms of an uncommonly long half-life and a comparatively large volume of distribution, both of which may prove beneficial to treating invasive fungal infections." (PMID 27919891, 2017). "The discovery of CD101 may expand the use and utility of echinocandins in the treatment of invasive fungal infections and for diseases not previously considered for echinocandin therapy." (PMID 27919891, 2017).
Candidemia (5 papers, 2016 to 2023). A form of invasive candidiasis where species of CANDIDA are present in the blood. "CD101 is currently in development as a once-weekly i.v. treatment of candidemia and as the first echinocandin candidate for topical treatment of vulvovaginal candidiasis." (PMID 27919891, 2017). "Two weekly doses of CD101 IV may provide a full course of echinocandin treatment for the majority of patients with candidemia, thus precluding the need to step down to an azole to complete treatment." (PMID 27919901, 2017).
colitis (4 papers, 2017 to 2024). Inflammation of the colon. "Recent experiments using a murine model of chronic colitis demonstrate that adoptive transfer of CD101-/- Tregs is associated with Th17 cell proliferation and more severe colitis." (PMID 29108000, 2017). "In line with our previous findings in the HDM-induced asthma model, the proportion of CD101+ eosinophils increased in colitis mice, indicating the presence of activated CD101+ eosinophils in colitis, and confirming the role of TGF-β signaling in promoting eosinophil activation." (PMID 39214980, 2024). "Notably, even in the DSS-induced experimental colitis model, the population of CD101+ eosinophils were augmented." (PMID 39214980, 2024). "In contrast, Cd101 and Cd34, which may serve as markers for Type 2 eosinophils were upregulated in eosinophils from asthmatic mice but not in eosinophils from mice with colonic inflammation." (PMID 34970274, 2021).
asthma (3 papers, 2024 to 2025). "The marked elevation of IL-18 is particularly notable when considering recent work highlighting the role of IL-18 in promoting a pathogenic CD101 + CD274 + eosinophil phenotype associated with the pathogenesis of both eosinophilic esophagitis and asthma." (PMID 41013452, 2025). "Notably, these eosinophils are increased in OVA- or HDM-induced asthma models and asthmatic patients correspondingly display an elevated CD101+ eosinophil level." (PMID 40276331, 2025). "Furthermore, CD101 positive and negative eosinophils differ in their airway localisation after Nippostrongylus brasiliensis infection and in an HDM asthma model." (PMID 40276331, 2025).
Candida infections (3 papers, 2016 to 2023). "Collectively, CD101 has great potential not only in treating invasive Candida infections but also in preventing emergence of resistance to currently approved echinocandin drugs." (PMID 27354115, 2016). "CD101 is a novel echinocandin under development for the treatment and prevention of systemic Candida infections." (PMID 27620474, 2016). "A total of 100,000 virtual patients with Candida infections were randomly resampled from patients enrolled in Studies CD101-IV-2-03 (STRIVE) and CD101-IV-3-05 (ReSTORE)." (PMID 38014945, 2023).
glioblastoma (3 papers, 2022 to 2025). The most malignant astrocytic tumor (WHO grade IV). "As for integrated diagnosis, the CD101 level was significantly the highest in glioblastoma with the IDH-wild type, followed by astrocytoma with the IDH mutant and oligodendroglioma with the IDH mutant and 1p/19q-codeleted." (PMID 35350788, 2022). "Specifically, we identified a significantly elevated transcript level of CD101 in low-grade glioma (LGG), glioblastoma (GBM), and all gliomas in comparison with that of the normal brain tissues." (PMID 35350788, 2022).
glioma (3 papers, 2019 to 2022). A benign or malignant brain and spinal cord tumor that arises from glial cells (astrocytes, oligodendrocytes, ependymal cells). "Given that, our data strongly implicated that M2-like macrophages in glioma TME were characterized by a high expression of CD101." (PMID 35350788, 2022). "The results revealed that an increased expression of CD101 was associated with significantly higher immune scores, stromal scores, and estimate scores among patients with glioma." (PMID 35350788, 2022). "After confounding for other variables, multivariate Cox regression analysis demonstrated that a high CD101 level was independently associated with increased risk of death among glioma patients (HR, 1.913; 95% CI, 1.287–2.843; p < 0.001)." (PMID 35350788, 2022). "Higher transcript levels in the NP were also found for CD101 encoding the transmembrane glycoprotein V7, a prognostic marker for gliomas, and CD109 encoding a protein that negatively regulates TGFβ signaling and is involved in tumorigenesis." (PMID 36406265, 2022). "Furthermore, multidimensional bioinformatics analyses and in-situ immunofluorescence staining indicated that CD101 was predominantly expressed on M2-like TAMs, in association with remodeling of the glioma immune microenvironment." (PMID 35350788, 2022). "To interrogate the underlying effect of CD101 in glioma, we carried out functional enrichment analyses based on DEGs between patients with a high or low expression level of CD101, in which a total of 2,469 DEGs were identified accordingly, with 2,052 upregulated and 417 downregulated genes." (PMID 35350788, 2022). "Taken together, these results implicated that CD101 expression might predict a unique immunosuppressive status of glioma immune infiltration, especially for T cell immune responses." (PMID 35350788, 2022). "Furthermore, the enrichment analysis implicated that the CD101 level could alter leukocyte migration and chemokine signaling pathway in glioma patients." (PMID 35350788, 2022). "Regarding WHO grade, CD101 expression was highest in grade 4 glioma, followed by grade 3 and grade 2 gliomas." (PMID 35350788, 2022). "It revealed that glioma patients with an elevated CD101 level were presented with unfavorable OS based on Kaplan–Meier survival analyses (p < 0.001)." (PMID 35350788, 2022). "Since the elevated CD101 expression was demonstrated to correlate with immune alterations and worsening prognosis in glioma patients, we then probed the role of CD101 in remodeling the tumor immune microenvironment." (PMID 35350788, 2022). "Correspondingly, in-situ immunofluorescence staining was adopted to verify the expression pattern and localization of CD101 in clinical glioma specimens at disparate grades." (PMID 35350788, 2022). "Taken together, a high CD101 expression level was correlated with worsening prognosis in glioma patients." (PMID 35350788, 2022). "To further clarify the functional role of CD101 in glioma, we did an enrichment analysis between high- and low-expression groups in accordance with CD101 mRNA expression." (PMID 35350788, 2022). "In terms of IDH status, the CD101 level remained markedly enhanced in glioma tissues subjected to the IDH-wild type." (PMID 35350788, 2022). "In the current study, we confirmed that the CD101 expression was significantly higher in the glioma than that of the normal tissue at both transcriptional and protein levels." (PMID 35350788, 2022). "Herein, we initially reported that a high CD101 expression in glioma is correlated with an increased infiltration of various immune cell types associated with immunosuppression, among which M2 macrophages have attracted our attention." (PMID 35350788, 2022). "To better understand the immune modulating functions of CD101, we further estimated the correlations between CD101 expression and diverse immunoregulatory molecules in glioma." (PMID 35350788, 2022).
glioma (continued). "To further probe the expression pattern of CD101 in glioma, we performed subgroup analyses by stratifying patients with disparate clinical characteristics, including WHO grade, histological type, age, IDH status, 1p/19q codeletion, and primary therapy outcome." (PMID 35350788, 2022). "More importantly, we further manifested that the number of CD163+ CD101+ cells was significantly abundant in the grade 4 glioma compared to that in grade 2 and grade 3 gliomas." (PMID 35350788, 2022). "Herein, by adopting bioinformatics methodology, we comprehensively illustrated the potential function and predictive value of CD101 in stratifying clinical prognosis among patients with glioma, for which a high CD101 level predicted an unfavorable clinical outcome in glioma patients." (PMID 35350788, 2022). "According to time-dependent ROC, the CD101 expression level had a relatively good performance in predicting 1-year (C statistics, 0.805), 2-year (C statistics, 0.830), and 3-year OS (C statistics, 0.850) in glioma patients." (PMID 35350788, 2022). "Correspondingly, it showed that CD101 expression could potentially interact with numerous immune-relevant genes, including CD276, CD274, CD80, CTLA4, and PDCD1, implying an immunoregulatory role of CD101 in the glioma immune microenvironment." (PMID 35350788, 2022). "Taken together, CD101 may serve as a novel biomarker in predicting clinical prognosis and immune status for glioma patients." (PMID 35350788, 2022). "Our work revealed that CD101 could serve as an independent prognostic indicator, the upregulation of which is positively correlated with unfavorable overall survival (OS) among glioma patients." (PMID 35350788, 2022). "Taken together, our results revealed that CD101 could serve as a novel indicator in predicting malignant phenotypes and clinical prognosis for glioma patients." (PMID 35350788, 2022). "Since a high CD101 expression could potentially predict a malignant phenotype of glioma, we therefore examined the predictive value of CD101 in determining clinical prognosis for glioma patients derived from TCGA database." (PMID 35350788, 2022). "Moreover, the in-situ expression of CD101 was further analyzed using HPA databases based on IHC staining, in which CD101 expression remained the highest in high-grade glioma, followed by low-grade glioma and normal brain tissue, consistent with the results from transcriptional analyses." (PMID 35350788, 2022). "CD101 expression was manifested to substantially alter immune cell infiltration in glioma TME, prompting us to gain insight into the cellular basis and distribution of CD101." (PMID 35350788, 2022). "Our findings revealed that M2-like TAMs uniquely expressed a high level of CD101, solidifying the relationship between CD101 and immunosuppressive TME in glioma." (PMID 35350788, 2022). "Additionally, the upregulation of CD101 was also noted in glioma tissues with 1p/19q non-codeletion." (PMID 35350788, 2022).
autoimmune disease (2 papers, 2022 to 2024). A disorder resulting from loss of function or tissue destruction of an organ or multiple organs, arising from humoral or cellular immune responses of the individual to their own tissue constituents. "Of note, recent work of CD101 mainly focused on its role in restraining T cells in inflammatory processes including infectious and autoimmunity diseases." (PMID 35350788, 2022). "The protein CD101, mainly expressed on several immune cells, has been demonstrated to exert potent effects on blunting T cell immune responses across infectious and autoimmunity diseases." (PMID 35350788, 2022).
eosinophilic esophagitis (2 papers, 2020 to 2025). Eosinophilic esophagitis (EoE) is a chronic, allergic disease of the esophagus characterized clinically by symptoms of esophageal dysfunction (including vomiting, dysphagia, feeding disorders, food impaction and abdominal pain) which persist after treatment with proton pump inhibitors (PPIs). "More recently, studies reported that CD101+CD274+ eosinophils were induced in the blood of patients with eosinophilic esophagitis and allergic asthma, and their levels were positively associated with disease severity." (PMID 32855977, 2020).
graft versus host disease (2 papers, 2017 to 2022). An immune system disorder that occurs after allogeneic hematopoietic stem cell transplant and is a reaction of donor immune cells against host tissues. "The immunoregulatory potential of CD101 was further strengthened by a subsequent study involving graft versus host disease, in which they manifested that an elevated expression level of CD101 on Tregs was associated with an increased capacity in restraining effector T cells." (PMID 35350788, 2022). "CD101 is expressed on CD4+ and CD8+ T-cells, dendritic cells and monocytes, and appears to alter CD4+/CD25+/FOXP3+ T regulatory cell (Treg) function based on both a murine graft-versus-host disease model, and through IL10 secretion from human dendritic cells." (PMID 29108000, 2017).
Sepsis (2 papers, 2022 to 2026). Sepsis is defined as life-threatening organ dysfunction caused by a dysregulated host response to infection. "Here, HH mice infected with a hyperyersiniabactin-producing Δfur rapidly develop sepsis symptoms, marked by an influx of immature CD101- neutrophils with impaired bactericidal capacity and heightened inflammation, whereas infected wild-type mice harbor functional mature CD101+ neutrophils." (PMID 42283579, 2026). "Sepsis plasma which lowered neutrophil half-life below 1000 min, or HD plasma complemented with recombinant histone H3 and G-CSF, increased the surface expression of CD11b, CD15, CD16, CD66b, CD10, CD101 and PD-L1 and these markers may enable the monitoring of lifespan modulation in patient blood." (PMID 35945238, 2022).
allergic rhinitis (1 paper, 2020). Inflammation of the nasal mucous membranes caused by an IgE-mediated response to external allergens. "In addition, a positive correlation between TNSS and the counts of blood and nasal CD101+CD274+ eosinophils was observed in subjects with allergic rhinitis." (PMID 32855977, 2020).
Allergy (1 paper, 2025). An allergy is an immune response or reaction to substances that are usually not harmful. "CD101 expression has also been used to subset eosinophils, with the CD101+ eosinophils corresponding to more pro-inflammatory functions and prevalent in pathological Type 2 responses, such as allergy and helminth infections." (PMID 41190814, 2025).